STAT6 (signal transducer and activator of transcription 6)
Diseases named in the same sentence as STAT6 in open-access papers (continued):
Sharing a sentence is not in itself a finding about the gene and the disease.
ovarian carcinoma (11 papers, 2002 to 2024). A malignant neoplasm originating from the surface ovarian epithelium. "Collagen triple helix repeat containing 1(CTHRC1), secreted by epithelial ovarian Cancer (EOC) cells, promoted M2-like polarization of tumor-associated macrophages (TAMs) by activating STAT6." (PMID 36524006, 2022). "In the present study, we found that high mRNA expression of STAT6 was correlated to a better OS for all the ovarian cancer patients, suggesting STAT6 has different prognostic significance across cancer types." (PMID 28536310, 2017). "High levels of STAT6 mRNA were significantly correlated to a favorable OS for all the ovarian cancer patients, HR =0.79 (0.69−0.9), P=0.00062." (PMID 28536310, 2017). "It is suggested that STAT1, STAT4, and STAT6 may be potential targets for the proper treatment of ovarian cancer." (PMID 36524006, 2022). "Based on our findings, STAT1, STAT4, and STAT6 may be viable therapeutic targets for ovarian cancer." (PMID 36524006, 2022). "Our results show that high mRNA expression of STAT1, STAT4, STAT5a, STAT5b, and STAT6, are correlated to a better OS of ovarian cancer patients, especially the high level of STAT1 and STAT4 are significantly related to a favorable OS for serous ovarian cancer patients." (PMID 28536310, 2017). "In the CSCs sorted from human ovarian cancer SKOV3 and A2780 cell lines, OCT4 can promote tumorigenesis by increasing the phosphorylation levels of JAK1 and STAT6 proteins of JAK/STAT signaling pathway." (PMID 34628473, 2021). "With regard to clinical stages, while STAT5a, STAT5b, and STAT6 were related to a positive OS both in stages I/II and III/IV ovarian cancer patients, STAT1 and STAT4 were correlated to a favorable OS in stages III and IV ovarian cancer patients." (PMID 28536310, 2017). "Here we found that phosphorylation of STAT1, as well as STAT4 and STAT6 (not shown) were simultaneously activated by PAF treatment in BRCA1-mutant ovarian cancer cells (UWB1)." (PMID 20576130, 2010). "Also, expression of p-STAT3 and p-STAT5 but not p-STAT1 and p-STAT6, were significantly higher in ovarian cancer cells compared to benign and normal tissues." (PMID 34358244, 2021). "High expression of STAT1, STAT3, STAT4, and STAT6 mRNA were correlated to a better OS in grade III ovarian cancer patients, but not in grade I or II ovarian cancer patients." (PMID 28536310, 2017). "Furthermore, high mRNA expression of STAT6 was correlated to a better OS in grade III ovarian cancer patients, but not in grade I or II ovarian cancer patients, implying that STAT6 may be a favorable prognostic indictor especially for poor differentiation ovarian cancer." (PMID 28536310, 2017).
synovial sarcoma (11 papers, 2014 to 2026). "While Bcl-2 is negative, CD34 and STAT6 are negative in synovial sarcoma and can thus aid in differentiating from SFT." (PMID 32566457, 2020). "CD34 and STAT6 were all negative in cases of synovial sarcoma." (PMID 32566457, 2020). "Immunohistochemical analysis demonstrated strong nuclear STAT6 expression and diffuse CD34 positivity, while epithelial, myoid/myofibroblastic, neural, and synovial sarcoma markers were negative, confirming the diagnosis of SFT." (PMID 41640935, 2026).
autoimmune disease (10 papers, 2016 to 2024). A disorder resulting from loss of function or tissue destruction of an organ or multiple organs, arising from humoral or cellular immune responses of the individual to their own tissue constituents. "All STAT family members (STAT1, STAT2, STAT3, STAT4, STAT5A, STAT5B, and STAT6) are related to autoimmune diseases." (PMID 35204186, 2022). "STAT6 is an important transcription factor in epithelial cell growth, and it is related to various autoimmune diseases and inflammatory conditions." (PMID 27906181, 2016). "Both C11orf30 and STAT6 are linked to various atopic and autoimmune diseases, although analyses indicated that the association of STAT6 with EoE is independent of sensitization status." (PMID 39126102, 2024). "Our studies suggest that inhibiting the STAT6 pathway to increase CD39 expression has the potential to treat autoimmune disease while stimulation of the pathway could improve T cell immunity." (PMID 35730568, 2022). "The ability of STAT6 inhibition to upregulate CD39 expression may be useful for treating autoimmune disease, while activation of the pathway in an immune response has the potential to prevent T cell dysfunction." (PMID 35730568, 2022). "Also, the STAT6 deficiency in a Lyn−/− background (Lyn is the negative regulator of Th2 immune response) facilitated the development of autoimmune diseases compared with those with intact STAT6 expression." (PMID 29184551, 2017). "Conversely, STAT6 inhibition greatly increased the frequency of T cells that expressed CD39 in an immune response, indicating its application in the treatment of autoimmune diseases." (PMID 35730568, 2022). "In infection models and autoimmune disease models, EZH2 inhibits the expression of genes and signaling pathways involved in anti-inflammatory function, such as PPARγ, SOCS1, STAT6, etc.." (PMID 35432300, 2022). "In conclusion, the deactivation of STAT6 and TSDR-targeted demethylation via CRISPR-TET1 is sufficient to induce iTregs with heightened stability and increased suppressive capacity, offering potential applications against inflammatory and autoimmune diseases." (PMID 38700792, 2024). "To determine whether the suppression of IL-4 and IL-21 induced downstream pathways could serve as a strategy to treat autoimmune diseases, we used three JAK inhibitors to suppress IL-4/STAT6 and IL-21/STAT3 activation in anti-IgM-treated Ramos cells." (PMID 35911775, 2022).
eosinophilic esophagitis (10 papers, 2016 to 2025). Eosinophilic esophagitis (EoE) is a chronic, allergic disease of the esophagus characterized clinically by symptoms of esophageal dysfunction (including vomiting, dysphagia, feeding disorders, food impaction and abdominal pain) which persist after treatment with proton pump inhibitors (PPIs). "Another possible explanation for our finding of STAT6 association with HCC development in NASH was supported by a recent study, which showed that variant of STAT6 rs167769 is strongly associated with eosinophilic esophagitis." (PMID 32283835, 2020). "Modern genomic technologies have revolutionized eosinophilia evaluation, with whole exome sequencing (WES) uncovering pathogenic STAT6 mutations in pediatric allergic cases and next-generation sequencing (NGS) identifying disease-associated STAT1 variants in familial eosinophilic esophagitis (EoE)." (PMID 41141324, 2025). "In addition, STAT-6 regulates CCL26 expression in esophageal cells and it has been strongly associated with inflammation in esophageal biopsies from patients with eosinophilic esophagitis." (PMID 35799778, 2022). "It has been demonstrated that omeprazole prevents STAT6 from binding to the eotaxin-3 promoter, which in turn inhibits the expression of eotaxin-3 by esophageal cells in eosinophilic esophagitis (EoE)." (PMID 36968499, 2023).
leukemia (10 papers, 2010 to 2025). A malignant (clonal) hematologic disorder, involving hematopoietic stem cells and characterized by the presence of primitive or atypical myeloid or lymphoid cells in the bone marrow and the blood. "In this study, we confirmed that P190 caused more severe leukemia with malignant phenotype than P210 and STAT6 was specifically activated in P190 cell lines." (PMID 36721266, 2023). "Therefore, we speculated that the more severe leukemia phenotype generated by P190 than P210 might be strongly associated with the additional aberrant activation of STAT6." (PMID 36721266, 2023). "Based on our previous leukemia cell line data demonstrating a correlation between STAT6 and MerTK phosphorylation, we assessed protein lysates from bone marrow derived macrophages (BMDMs) cultured with (or without) AML cells by immunoblot." (PMID 36960055, 2023). "We confirmed that inhibition of p-STAT6 had a better anti-leukemia effect in vitro in P190 cells than in P210 cells." (PMID 36721266, 2023). "Taken together, we verified that inhibition of p-STAT6 had a more effective anti-leukemia effect in P190 mouse model than in P210 mouse model." (PMID 36721266, 2023). "We previously reported that in leukemia cells, MerTK inhibition using short-hairpin RNA and MerTKIs decreased STAT6 phosphorylation." (PMID 36960055, 2023). "Phospho-STAT6 was significantly increased in all leukemia groups in comparison to the normal CD34+ samples." (PMID 25568664, 2014). "Moreover, knockout or pharmacological inhibition of STAT6 specifically sensitized ALL cells to the central anti-leukemia drug cytarabine (Ara-C) and increased the incidence of Ara-C-induced apoptosis without altering the normal growth of ALL cells." (PMID 40897694, 2025). "Here, we found that MRX2843 treatment similarly decreased STAT6 phosphorylation in leukemia-exposed macrophages, providing a plausible mechanism by which MerTK inhibition leads to macrophage repolarization from cancer-promoting toward a classically activated phenotype." (PMID 36960055, 2023). "Concerned that inhibition of p-STAT6 had a powerful anti-leukemia effect, we wondered whether p-STAT6 suppression could improve the sensitivity of Ph+ ALL cells to IM." (PMID 36721266, 2023). "Therefore, we verified that inhibition of p-STAT6 had a more effective anti-leukemia effect in P190 than that in P210 in vivo." (PMID 36721266, 2023). "To investigate whether the IL4-induced Stat6 activation was responsible for the depletion of leukemia cells, we first introduced ectopic Cas9 expression in the leukemia cells and sequentially a Stat6 sgRNA." (PMID 28819278, 2018). "To assess whether Stat6 disruption rendered the leukemia cells resistant to IL4, we monitored the percentage of sgRNA-expressing cells by tracking GFP+ cells during IL4 stimulation." (PMID 28819278, 2018). "We found that short exposure of leukemia cells to IL4 resulted in phosphorylation of Stat6." (PMID 28819278, 2018). "The leukemia cells that expressed the Stat6 sgRNA had a selective proliferative advantage upon IL4 treatment and exhibited reduced apoptosis, demonstrating that IL4 depletes the leukemia cells in a Stat6-dependent manner by inducing apoptosis." (PMID 28819278, 2018). "However, with respect to daunorubicin, our data from HeLa cells indicate that STAT6, and in particular PDAP1, appear to function in the cellular response to daunorubicin and warrant further investigation in leukemia cells." (PMID 29656114, 2018). "We first performed oligoprecipitation experiments in a monocytic leukemia cell line, THP-1, and both endogenously expressed PPARγ and STAT6 could be pulled down with wild-type MacPPRE." (PMID 21093321, 2010). "To validate the implications of STAT6 knockout in vivo, we used a mouse leukemia xenograft model by injecting parental REH or STAT6-knockout REH cells into NDG mice and observed no significant impact of STAT6 knockout on leukemogenesis in vivo." (PMID 40897694, 2025).
schistosomiasis (10 papers, 2009 to 2023). An infectious disease caused by parasitic trematodes of the genus Schistosoma that colonize human blood vessels and release eggs that can cause granulomatous reactions leading to acute (swimmer's itch or acute schistosomiasis syndrome) or chronic disease. "Other polymorphisms located in the promoter region or other regions of STAT6 gene have been associated not only with schistosomiasis in Mali, but also with Ascaris lumbricoides infections." (PMID 36889485, 2023). "Genetic studies have revealed associations between SNPs in genes encoding cytokines and TFs and susceptibility to schistosomiasis, including in STAT6, IL4, IL5, IL10, and IL13." (PMID 35759449, 2022). "IL13 and IL4 regulate STAT6 expression which in turn regulates IgE class switching and STAT6 variants are also associated with schistosomiasis." (PMID 33659002, 2021). "With the deletion of STAT6, the rs3024974T/T variant among infected children indicated the need for the STAT6 promoter gene in provoking schistosomiasis susceptibility in Nigeria." (PMID 31886304, 2019). "We thus next examined STAT6 and PPAR-γ signaling to address the mechanisms by which Cx3cr1 deficiency skews macrophages towards M2 polarization during acute schistosomiasis." (PMID 26035381, 2015). "Most notably, Arg1 mRNA was not reduced, yet Arg1 expression in macrophages is predominantly driven by an IL-4Rα/STAT6-dependent mechanism in schistosomiasis." (PMID 25211233, 2014). "Because production of the soluble IL-13Rα2 is IL-4Rα-, IL-13Rα1-, and Stat6-dependent, these data combined with the schistosomiasis studies suggested that the Retnla−/− mice were developing stronger IL-4/IL-13 responses following infection." (PMID 19381262, 2009). "IL13, IL4, IL5, and STAT6 are also involved in regulation of the Th2 response to schistosomiasis." (PMID 33659002, 2021). "The experimental Schistosomiasis-associated PAH potentially depends on upregulation of IL-13, which can activate TGF-β1 via phospho-STAT6 signaling, or via increased matrix metalloproteinase-inducing muscular hypertrophy and periadventitial fibrosis in pulmonary arteries." (PMID 34122072, 2021).
Cerebral ischemia (9 papers, 2015 to 2025). Restriction of arterial blood supply to the brain associated with insufficient oxygenation to support the metabolic requirements of the tissue. "SNHG4 regulates STAT6 and suppresses inflammation by adsorbing miR-449c-5p in microglia during cerebral ischemia-reperfusion injury." (PMID 36275741, 2022). "The knockout of STAT6 has been found to result in the dysfunction of dead neuron clearance and increased expression of pro-inflammatory factors in mice with cerebral ischemia." (PMID 35663575, 2022). "Cerebral ischemia has been shown to reduce levels of the transcription factor signal-transducer-and-activator-of-transcription-6 (STAT6), which is also degraded by calpain." (PMID 26050199, 2015). "Similarly, Loureirin B shifts microglia from M1 to M2 phenotypes through STAT6 signaling, protecting against cerebral ischemia–reperfusion injury." (PMID 40392018, 2025). "Therefore, SNHG4 regulates STAT6 and inhibits inflammation by adsorbing miR-449c-5p in microglia during cerebral ischemia-reperfusion injury." (PMID 36275741, 2022). "Moreover, treadmill training could relieve cerebral ischemia‐reperfusion injury by facilitating M2 microglia activation through IL‐4 upregulation mediated by the JAK1/STAT6 pathway." (PMID 37143406, 2023). "Therefore, STAT6 might play an essential role in regulating neuroinflammation induced by cerebral ischemia." (PMID 35663575, 2022).
COVID-19 (9 papers, 2021 to 2025). A disease caused by infection with severe acute respiratory syndrome coronavirus 2. "p-STAT6 signaling, the other major mechanism studied in podocytes, was activated downstream of IL-4Rα by COVID-19 cocktails in the ZHX2+/+ podocytes and reduced in ZHX2hypo/hypo cells." (PMID 37040185, 2023). "Monocytes from patients with COVID-19 express high levels of genes associated with inflammation including IL17RA, JAK-STAT-associated gene STAT6, and inflammatory protein-encoding genes TNFRSF1B and ANXA2." (PMID 36992700, 2023). "Therefore, both ZHX- and p-STAT6–mediated mechanisms related to podocyte IL-4Rα are active in COVID-19 models and ZHX mechanisms only in the common cold model." (PMID 37040185, 2023). "One of the most strongly affected TFs is STAT2, together with STAT6, which could be linked to the aberrant IFN signaling in monocytes in COVID-19." (PMID 36443794, 2022). "Pathomorphological studies of the lungs of those patients who died from COVID-19 showed the presence of pneumocytes, CD68+ macrophages, and CD3+ T cells with the activation of STAT6 expression in the inflammatory infiltrates." (PMID 37109672, 2023). "We also observed COVID-19-specific enrichment of signaling genes such as MAP3K1, which helps activate JNK and ERK pathways, and STAT6, which is involved in IL-4 and IL-13 signaling." (PMID 36992700, 2023). "A decrease in the expression of the following genes was also observed in COVID-19-positive patients: RAPGEF1 (p = 0.0091), MAP2K1 (p = 0.038), CEBPB (p = 3.3 × 10−6), STAT6 (p = 0.041), JUN (p = 1.4 × 10−8), PRKACA (p = 0.021), and AKT1 (p = 1.3 × 10−6)." (PMID 36298734, 2022). "Asynchronous activation of nuclear targets of p-STAT5 and p-STAT6 in BALB/cJ compared with BALB/c mice could account for some aspects of reduced injury and mortality from COVID-19 cocktail injection in BALB/cJ mice." (PMID 37040185, 2023). "Notably, in our RNA-Seq data set, Stat6 and Gata3 were not upregulated during COVID-19 in mice, which may reflect an inability to detect changes in these mRNAs at that time point." (PMID 34185704, 2021).
fibrosis (9 papers, 2016 to 2026). the formation of excess fibrous connective tissue in an organ or tissue in a reparative or reactive process. "Reintroduction of miR-135b may be useful in STAT6-driven fibrosis." (PMID 27113293, 2016). "This highlights the important role played by IL-13/STAT6 axis in cancer development in NASH, in both lower and advanced fibrosis grades patients." (PMID 32283835, 2020). "Similarly, in our studies, we have shown that IL-6 and IL-10 were increased in patients with fibrosis, together with STAT4 and STAT6." (PMID 30205811, 2018).
allergic rhinitis (8 papers, 2012 to 2025). Inflammation of the nasal mucous membranes caused by an IgE-mediated response to external allergens. "It is indicated that the suppression of STAT6 using small interfering RNA (siRNA) improves the Th2/Treg ratio in patients with allergic rhinitis." (PMID 30116273, 2018). "The presence of STAT6 immunoreactive cells with nuclear localisation of STAT6 in the nasal mucosa of atopic allergic rhinitis may be the result of a selective accumulation of Th2 cells in this disease." (PMID 22401596, 2012).
breast tumor (8 papers, 2014 to 2023). "STAT3, STAT5, and STAT6 are strongly activated in breast tumors and act as mammary oncogenes." (PMID 34090412, 2021). "We found that IR-induced IL-4 signaling also promoted the growth of primary breast tumors and their metastasis to lung in nude mice by activating IL-4/JNK/β-catenin/Stat6 signaling." (PMID 27895317, 2016). "MDA-231 breast tumor cells exposed to IFN-γ or IL-13 induced phosphorylation of STAT1 and STAT6, respectively." (PMID 24911872, 2014). "Similarly, previous studies have demonstrated that STAT6 inhibition with AS1517499 suppresses the anti-inflammatory macrophage phenotype in vitro, whilst leading to reduced primary breast tumour volume and lower incidence of liver metastasis in vivo." (PMID 35359423, 2022).